TK1 (thymidine kinase 1)
Diseases named in the same sentence as TK1 in open-access papers (continued):
Sharing a sentence is not in itself a finding about the gene and the disease.
tumor (continued). "TK1 might be secreted from tumor cells that are growing actively." (PMID 38480789, 2024). "Furthermore, we revealed that Tregs may affect tumor occurrence, progression, and prognosis by modulating the expression of TK1 within the TME." (PMID 37767092, 2023). "Thus, levels of TK1 in blood of patients are a correlate of tumor burden." (PMID 37377898, 2023). "Furthermore, several studies identified TK1’s correlation with tumor aggressiveness." (PMID 37373974, 2023). "Besides, we selected 5 key genes (SRSF2, HELLS, PNN, TK1, and CKS2) in hallmark_E2F_targets in Pathcards database and validated that they are associated with overall survival, metastasis, and tumor stage of patients with PCa through multiple online database validation." (PMID 35392496, 2022). "Therefore, the generation of therapeutics specific for TK1 could enable us to explore the potential of TK1 as a tumor target." (PMID 35239730, 2022). "Thus, the use of human sdAb molecules targeting TK1 may enable us to better explore the potential of TK1 as a tumor target in proliferating malignant cells." (PMID 35239730, 2022). "In addition, activated mast cells could release tissue kallikrein (TK1), which in turn boosts the viability and invasion of tumor cells through upregulation of angio-permeability." (PMID 35096063, 2022). "TK1 ablation inhibits tumor malignant behavior and may serve as a therapeutic target for PCa." (PMID 35559045, 2022). "Therefore, further studies of TK1 may improve our understanding of HCC immunobiology and could help to break immune tolerance in HCC with poor immunogenicity, thus providing a theoretical basis for the development of anti-TK1 immunotherapy in this tumor type." (PMID 35127491, 2021). "Together, these results suggest that TK1 may play an important role in tumor growth and metabolism." (PMID 35127491, 2021). "Furthermore, activated MCs in EC tissue express high levels of tissue kallikrein (TK1), which may subsequently generate mitogenic kinin, a promoter of tumor cell growth." (PMID 33995371, 2021). "However, new evidence indicates an emerging role of TK1 as a possible tumor target." (PMID 32317865, 2020). "Therefore, when normal cells divide, there is very little TK1 in the body, while malignant tumor cells proliferate vigorously, and the regulation factors of cell cycle are out of balance, losing the normal periodicity, TK1 increases significantly correspondingly." (PMID 32202305, 2020). "Interestingly, LMNB1, RACGAP1, TK1, and ZWINT were all positively associated with tumor purity." (PMID 31306099, 2019). "This underlies that TK1 activity may in fact reflect tumor biology (i.e. tumor proliferation) rather than tumor burden." (PMID 29662653, 2018). "Furthermore, serum TK1 activity was significantly associated with tumor size, lack of ER and PgR, tumor grade, and molecular subtype." (PMID 29162134, 2017). "Therefore, TK1 activity indirectly reflects the state of tumour cell proliferation." (PMID 24944599, 2014). "Thus, serum TK1 should be a good marker for tumour cell proliferation." (PMID 19396699, 2009). "By integrating multiomics data, we identified TK1, NME4, and RRM2B as key biomarkers that influence tumor progression, immune modulation, and treatment response." (PMID 41584726, 2026). "Collectively, these multi-platform analyses consistently indicate that TK1 is overexpressed in OSCC and correlates with tumor progression and lymph node metastasis." (PMID 40564887, 2025). "This study demonstrates that TK1 is consistently overexpressed in OSCC and plays a functional role in promoting tumor cell motility." (PMID 40564887, 2025). "Protein expression data retrieved from the CPTAC database further confirmed this trend, demonstrating that TK1 protein levels were significantly higher in HNSC tissues compared to normal tissues, and progressively increased with tumor stage." (PMID 40564887, 2025).
tumor (continued). "Combining CRP with other biomarkers, such as thymidine kinase 1 (TK1), can enhance the sensitivity for early tumor detection." (PMID 40351765, 2025). "Tumor-related messenger RNAs (mRNAs), such as TK1 mRNA, MUC1 mRNA, GalNAC-T mRNA, C-myc mRNA, and survivin mRNA, have been suggested as specific biomarkers for tumor progression and prognosis." (PMID 40942076, 2025). "This study found that in cancer types with over 12 tumor and para-cancer tissues, the genes RRM2, TK1, CCNB1, DLGAP5, CCNA2, MYBL2, and HJURP were repeatedly overexpressed across various cancer tissues." (PMID 39669580, 2024). "For example, in LC, miR-320b suppresses angiogenesis and tumor growth by downregulating the expression of IGF2BP2 and thymidine kinase 1 (TK1)." (PMID 39295872, 2024). "A four-gene signature, consisting of TYMS, GAPDH, TK1, and DHFR, was enough to diagnose the CIMP phenotype and identify tumours eligible for immunotherapy." (PMID 38540202, 2024). "FKBP4, TK1, HERPUD1, and CLEC3B levels were measured and verified in clinical samples (tumor tissues)." (PMID 37341998, 2023). "Joint detection of serum TK1, PCDGF, CYFRA21-1, NSE, and CEA, plus enhanced CT scan outperformed stand-alone detection using either the serum tumor markers or enhanced CT scan (P < 0.05)." (PMID 35368891, 2022). "The most significant target genes were putative tumor oncogenes/promoters (TK1, KIF2C, UBE2C, AURKB) and potential tumor suppressors (CALCOCO1, CIRBP, KLHDC1, CBX7)." (PMID 36358602, 2022). "In order to elucidate the effects of CCAT2 and TK1 on the growth of transplanted ESCC tumors in vivo, we conducted subcutaneous tumor xenografts experiments in nude mice." (PMID 34386421, 2021). "Some tumor biomarkers varied as the cell cycle progressed, such as CA9, TK1 and EGFR, which were more abundantly expressed at early S stage." (PMID 34691667, 2021). "This means that tumours with the highest expression of TYMP and TK1, which would result in high FdUMP levels, also had high ABCC5 expression, which would result in efflux of FdUMP." (PMID 34132895, 2021). "For example, the smaller cell cluster B4b was a highly proliferative tumor with cells at either the G2/M, or S phase and displayed high expression of MKI67, CDK4, and other proliferative markers such as PCNA, TK1, and TYMS." (PMID 34001881, 2021). "Overall, our study identified a tumor-promoting lincRNA — lincNMR — and unveils its mechanism along a YBX1–RRM2 / TK1 / TYMS axis in regulating nucleotide metabolism and governing the cancer cell fate between proliferation and senescence." (PMID 32587247, 2020). "Thus, TK1 may be a tumor target that can be used for therapy in multiple solid malignancies." (PMID 32317865, 2020). "FLT allows the direct measurement of cellular thymidine kinase-1 (TK1), which has been reported to be proportional to the proliferation activity of a tumour." (PMID 32382870, 2020). "In this study, we identified TK1 as a metabolic enzyme that is overexpressed in LUAD and promotes LUAD tumor and metastatic growth." (PMID 31589613, 2019). "Thymidine kinase 1 (TK1), a cell cycle-dependent protein, has been extensively reported as a tumor biomarker, but its role in PCa remained unclear." (PMID 31306099, 2019). "In this study, we identified that decreased expression of TFAM impaired the proliferation of tumour cells by inducing G1/S phase arrest and reducing the expression of E2F1, phospo‐Rb, PCNA and TK1." (PMID 31062473, 2019). "For example, drugs that inhibit the de novo pathway of DNA synthesis can alter the activity of TK1, and thus that of [18F]FLT phosphorylation and its trapping in the tumor cell." (PMID 27798786, 2017). "Endogenous thymidine and [18F]FLT compete for tumor cell uptake via ENT1 and phosphorylation by TK1." (PMID 27798786, 2017). "we found that expression of TK1, TYMS and DTYMK enhanced tumor sphere formation capability and increased ALDH1 positive populations in well-differentiated HCC cells." (PMID 29100421, 2017).
tumor (continued). "This is supported by the significant reduction in tumor TK1 mRNA following anastrozole at C1D1 and a reduction of serum TK1 activity in ~ 50% of patients." (PMID 29162134, 2017). "As a consequence, tumor cells can upregulate the thymidine salvage pathway, resulting in increased TK1 activity and redistribution of ENT1 to the cell surface, which leads to enhanced [18F]FLT uptake and trapping in the tumor cell." (PMID 27798786, 2017). "Knockdown of TK1, TYMS and DTYMK reduced capability of forming tumor spheroids as shown in results of microscopy and in assays of 2 serial passages." (PMID 29100421, 2017). "Elevated TK1 expression is observed during cell proliferation, and therefore, [18F]FLT PET is a potential marker for tumor cell proliferation." (PMID 27798786, 2017). "Several studies have reported the individual expression pattern and function of each hub (TK1, CSNK2B, VIM, YWHAB and HSP90AB1) in different tumors and tumor models in vitro." (PMID 27527857, 2016). "The expression levels of BIRC5, TK1, TNNT1 and MMP9 were found to be positively related to tumor recurrence after cystic resection." (PMID 25970782, 2015). "Clinical relevance of high levels of TK1 and TYMP was then assessed on human HCC tumor and normal liver tissues with immunohistochemical (IHC) analysis." (PMID 25881156, 2015). "Distinguishing from a few tumor specific biomarkers (PSA, AFP, HCG etc), thymidine kinase 1 (TK1, ATP; thymidine 5′-phosphotransferase; EC.2.7.1.21) is one of the non-specific tumor markers that can be measured in continuously dividing cells." (PMID 24621590, 2014). "TK1 is catalytically active only during the S phase; therefore, [18F]FLT uptake provides a measure of the S-phase fraction of a tumor." (PMID 24073202, 2013). "Since ATP is a co-factor for TK1, a decrease in ATP level will possibly decrease uptake of [18F]FLT, and a change in ATP tumor level is likely to account for some of the [18F]FLT changes we found in this study." (PMID 23308217, 2013). "18F-fluorothymidine (18F-FLT) positron emission tomography (PET) is used to assess tumor proliferation, since the FLT uptake level reflects thymidine kinase-1 (TK-1) activity." (PMID 24137387, 2013). "Quantitative relationships between PET, thymidine kinase 1 (TK1) protein levels and immunostaining for proliferation markers (Ki67, TK1, PCNA) were evaluated using imaging-matched tumor specimens." (PMID 23554961, 2013). "In fact, a large subset of patients classified with very favorable outcome shared a common molecular tumor phenotype characterized by ER-positive and/or ERBB2-negative status and low proliferation (low levels of E2F1 as well as BIRC5,TYMS,TOP2A and TK1)." (PMID 17535433, 2007). "Functional validation experiments targeting TK1, including RNA interference followed by proliferation (CCK‐8, EdU), migration (Transwell), and wound healing assays, substantiated its role in promoting tumor aggressiveness." (PMID 41584726, 2026). "After anastrozole monotherapy, patients experienced a decline in Ki-67 protein expression in the tumor tissue but not a notable alteration in TK1 activity." (PMID 40133412, 2025). "Moreover, investigations of clinical samples have revealed a robust relationship between the expression levels of TK1 and PRMT1 and tumor volume, microvascular invasion, and tumor stage in patients with HCC." (PMID 41256732, 2025). "In contrast, age of onset, menopause status, tumor invasion and surgical approach seemed to be not related to TK1 expression." (PMID 38480789, 2024). "This analysis revealed that seven cell populations exhibited a significant correlation with poorer patient outcomes, including tumor cell cluster 3 (highly expressing S100A2), cluster 8 (TK1), cluster 10 (PTTG1), cluster 12 (IGFBP5), cluster 13 (ISG15), cluster 16 (UPP1), cluster 17 (IL13RA2)." (PMID 38331898, 2024). "Collectively, these findings indicated that TK1 might play different roles in the LGG and GBM tumor microenvironments." (PMID 36831773, 2023).
tumor (continued). "STK1p was detected in 95 voluntary blood donors (no malignant tumours or infectious diseases were self-reported) using either TK1-IgY-pAb or hTK1-IgY-rmAb#5 based on the semiautomatic ECL dot blot assay." (PMID 36969497, 2023). "TK1 and SGOL2 have been identified as tumour progression factors in other tumour entities." (PMID 37024667, 2023). "Increased concentrations of TK1 are found in most tumor diseases and therefore, TK1 is not specific for PCa." (PMID 36982234, 2023). "Moreover, the expression of SNHG4, TK1, AURKA, RRM2 and EZH2 in the tumor tissues was found to be significantly elevated after SNHG4 overexpression." (PMID 37596700, 2023). "Interestingly, the expression pattern of ABCC5 in individual tumours closely followed that of TYMP and TK1." (PMID 34132895, 2021). "Furthermore, the transcriptomics profiling revealed that tumor biomarkers changed as the cell cycle progressed and biomarkers of CA9, TK1 and EGFR were more abundantly expressed at early S stage." (PMID 34691667, 2021). "Baseline TK1 activity was modestly correlated with central Ki67 (r = 0.315, analysis of variance P = 0.02), but not with tumor size (P = 0.379), lymph node status (P = 0.355) or IHC subtype (P = 0.144)." (PMID 33714010, 2021). "For example, the smaller cell cluster B4b was a highly proliferative tumor with cells at either the G2/M, or S phase (right two panels) and displayed high expression of MKI67, CDK4, and other proliferative markers such as PCNA, TK1, and TYMS." (PMID 34001881, 2021). "18F-FLT is phosphorylated by thymidine kinase-1 (TK-1) but cannot further participate in DNA synthesis and is trapped within the tumor cells due to the lack of the 3′-hydroxy group." (PMID 34771622, 2021). "Based on a comprehensive analysis of TK1-related immune prognosis in HCC, the aim of this study was to better understand the potential role of TK1 in the pathogenesis of HCC, as well as its potential as a tumor biomarker and therapeutic target." (PMID 35127491, 2021). "Furthermore, a positive correlation was found between tumour expression of TYMP and TK1 (r = 0.77, p = 0.0013)." (PMID 34132895, 2021). "However, little is still known about the expression of TK1 in HCC, its relationship with the clinical pathology and molecular characteristics of this disease, and its role in shaping the tumor immune microenvironment." (PMID 35127491, 2021). "Specific pathways and protein interactions of TK1 with other factors that lead to tumor cell progression have not been extensively explored." (PMID 33292474, 2020). "To date, there is no identified functional difference between TK1 protein and TK1 mRNA in normal and tumor cells." (PMID 33292474, 2020). "The expression of LMNB1, TK1, ZWINT, and RACGAP1 was positively associated with tumor purity, while no or weak associations were observed for hub genes and infiltrating immune cells in PCa tissue samples." (PMID 31306099, 2019). "We found that TK1 can promote LUAD tumor growth and metastasis in a non-canonical manner by activating Rho GTPase activity and growth and differentiation factor 15 (GDF15) expression." (PMID 31589613, 2019). "Neither serum TK1 activity nor tumor Ki-67 value significantly changed in the palbociclib-resistant category." (PMID 29162134, 2017). "Furthermore, tumor tissues from the established Bel-7402 mouse model had consistently high expression of TYMP and TK1 by IHC analysis, whereas the mouse normal liver tissue showed only basal level of either protein (panels F-H versus panels E)." (PMID 25881156, 2015). "Development of TK1 antibody-based methods demonstrated that the concentration of STK1 protein may be used for the prognosis and monitoring of tumor therapy in several types of solid tumor diseases." (PMID 25881026, 2015).
tumor (continued). "In a re-analysis of those data, one prominentgene-expression feature included genes regulating the cell-cycle (e.g. CCNE1,CDK1, CDC25A), and involved in DNA replication(e.g. POLE2, MCM4, TK1) andchromosome dynamics (e.g. SMC4, CENPE), ostensiblyreflecting tumor cell proliferation levels." (PMID 21629784, 2011). "TK1 dynamics reflect tumor proliferation but did not significantly predict chemotherapy response." (PMID 42158955, 2026). "This analysis confirmed the association of TYMS, TK1, SHMT2, MTHFD2, and DHFR expressions with the main prognosis markers (hypermutation, MSI, iCluster, expression subtype, and tumour stage) while MTHFD1, and not MTHFD2, was more strongly associated with methylation status." (PMID 38540202, 2024). "Nevertheless, using TK1 as a single tumour marker is not recommended, but a serial measurement of the enzyme might be superior." (PMID 36495211, 2023). "Notably, we did not identify the methylation levels of TK1 between tumor and normal samples; thus, further exploration is still required." (PMID 36831773, 2023). "Possibly, TK1 is released from proliferating, though non-viable tumor cells." (PMID 36982234, 2023). "Although it remains unclear why TK1 is localized to the cell surface of multiple cancer cell lines, the flow cytometry data and ADCC results described here suggest that it could be feasible to harness the immune system against tumor cells expressing mTK1." (PMID 35239730, 2022). "Therefore, if the pathway for removal of damaged cells had been the same in normal tissues and tumour, then the serum level of TK1 would not have been capable of reflecting a property of the tumour." (PMID 32423477, 2020). "However, despite these data suggesting an important role for TK1 in cancer pathogenesis, no study thus far has analyzed the functional effect of TK1 inhibition on tumor growth and metastasis." (PMID 31589613, 2019). "However, knockdown of DCK failed to inhibit LUAD tumor growth, indicating that the DNA damage that results from TK1 knockdown is unlikely to play a role in the inhibition of LUAD tumor growth and metastasis." (PMID 31589613, 2019). "On the other hand, ET does not interact directly or indirectly with TK1 activity, and changes in TK1 activity may entirely reflect changes in tumor proliferation in this context." (PMID 29662653, 2018). "However, the absolute value of serum TK1 activity at C1D15 did not predict the persistent tumor proliferation assessed by Ki-67 staining, because all six cases had a serum TK1 activity below the detection limit of 20 Du/L." (PMID 29162134, 2017). "It is also reported that FLT level does not reflect tumor proliferation but TK1 activity." (PMID 27957722, 2016). "However, thymidylate synthase (Tyms) and thymidine kinase (TK1) were not significantly different between TAg positive and WT tumours." (PMID 26680231, 2015). "However, the results did not correlate to the progressive levels of TK1 in tumor tissues, suggesting a complicated mechanism, possibly involving catabolism by TYMP." (PMID 25881156, 2015). "However, it soon became clear that [18F]FLT tumor uptake does not always correlate with the expression of proliferation markers such as Ki67 or TK1." (PMID 23861829, 2013). "However, it cannot be excluded that TK1 is excreted from living normal and tumour cells in different ways." (PMID 22247653, 2011). "The level of TK1 is very low in non-proliferating cells but increases dramatically at late G1 to late S-phase/early G2 phase during the cell cycle in proliferating cells and tumour cells." (PMID 19396699, 2009). "Consequently, the study concluded that TK1 alone is not a highly effective tumour marker." (PMID 40830177, 2025). "Besides the complicated interplay between the cell loss from the tumor and the normal environmental cells, which might determine the blood level of TK1, tumor aneuploidy cannot be excluded as a source of higher baseline levels of sTK1." (PMID 34771604, 2021).